INS (insulin)
Diseases named in the same sentence as INS in open-access papers (continued):
Sharing a sentence is not in itself a finding about the gene and the disease.
Hepatic steatosis (continued). "Overall, our data suggest that the beneficial effects of MaR1 on insulin sensitivity and liver steatosis might also rely on its ability to control the secretome of eWAT, liver and muscle, and therefore the crosstalk between key metabolic organs." (PMID 37371501, 2023). "In addition, insulin significantly ameliorated hepatic steatosis and increased the glycogen content in the liver of T1DM mice." (PMID 36756089, 2023). "Interestingly, a recent study revealed that a combination of bis (α-furancarboxylato) oxovanadium and metformin ameliorates hepatic steatosis in high-fat diet-induced obese mice by alleviating hepatic inflammation and enhancing the insulin signaling pathway." (PMID 38011086, 2023). "We employed body mass index (BMI), waist circumference (WC), serum fasting insulin levels, triglycerides, and liver enzymes in various equations to determine the Fatty Liver Index, Hepatic Steatosis Index, NAFLD Liver Fat Score, and the Triglycerides and Glucose Index." (PMID 38222178, 2023). "Therefore, molecular mechanisms that regulate adipocyte insulin sensitivity during adipocyte expansion in the setting of overnutrition are also anticipated to influence fatty acid flux to the liver and hepatic steatosis." (PMID 36749637, 2023). "Dietary leucine supplements in drinking water were found to improve glucose tolerance and insulin sensitivity by decreasing tyrosine phosphorylation of insulin receptor substrate-1 (IRS-1) and decreasing insulin-stimulated serine phosphorylation of AKT then reducing hepatic steatosis." (PMID 37432261, 2023). "Although few studies distinguish pre- versus post-menopausal women, evidence suggest that women at reproductive age are protected against fatty liver disease through estrogen signaling mainly via Estrogen receptors alpha (ERα) to improve liver insulin sensitivity and limit hepatic fat accumulation." (PMID 37854184, 2023). "In this review, the efficacy and related mechanisms of SFN in the treatment of liver diseases, including fatty liver disease, hepatic insulin resistance, xenobiotic-induced liver injury, hepatic ischemia-reperfusion injury, and hepatocellular carcinoma (HCC), were summarized." (PMID 37705537, 2023). "Multiple studies have suggested that elevated DG levels may impair insulin action in fatty liver disease." (PMID 37124226, 2023). "Notably, we show that MO affects hepatic lipid metabolism differently in obese female and male offspring together with sex-specific alterations of the expression of genes involved in insulin signaling, liver steatosis, inflammation, fibrosis, and carcinoma." (PMID 36195702, 2022). "In this study, our data showed that FTZ alleviated the expression of PPAR-γ and CD36 in livers from HFD-fed mice at least in part, which may impact the severity of hepatic steatosis as well as improve whole-body insulin sensitivity." (PMID 35784533, 2022). "In addition, several researchers found that APS enhanced insulin sensitivity and ameliorated hepatic steatosis by regulating the expression of GSK3β, although these results were contradictory." (PMID 36059978, 2022). "We hypothesized that long‐term liver‐directed mitochondrial uncoupling would reduce ROS production and increase longevity in mice, as well as improve insulin sensitivity, hepatic steatosis, and hepatic inflammation." (PMID 35088525, 2022). "Consistent with the liver steatosis, the Hsd17b1333A/A mice increased serum insulin levels." (PMID 36323699, 2022). "EE exposure increased insulin signaling and reduced hepatic steatosis in the liver of HFD-fed mice." (PMID 35112705, 2022). "In addition to these findings, the incorporation of this plant as part of an HFD led to a concomitant improvement in fasting insulin resistance and other metabolic factors that facilitate reduction in hepatic steatosis." (PMID 36364811, 2022).
Hepatic steatosis (continued). "We next investigated effects exerted by 2′-FL supplementation during the experiment that may explain the reduced development of liver steatosis, with particular emphasis on gut permeability and insulin resistance." (PMID 35782914, 2022). "The leptin may contribute to hepatic steatosis by promoting insulin resistance and by altering insulin signaling in hepatocytes, which consequently promote increased intracellular fatty acid." (PMID 35883850, 2022). "In our present work, we found that Trim31 has the ability to suppress liver steatosis and improve insulin signaling and hepatic inflammation by promoting Rhbdf2 degradation via K48-linked ubiquitination, further restraining Rhbdf2-MAP3K7 activity and downstream events." (PMID 35217669, 2022). "Furthermore, palmitoleic acid acts as an adipokine, a signaling molecule produced by adipocytes, stimulating the effects of insulin on the muscles and reducing hepatic steatosis." (PMID 35676689, 2022). "Our results showed that hepatic steatosis, but not the degree of liver fibrosis, was associated with different measures of insulin sensitivity in patients with morbid obesity and T2DM." (PMID 36336684, 2022). "The mean serum insulin was significantly higher for individuals with Level 1 MetS (approx. 9 mU/L for both genders) compared with metabolically normal individuals, as was the prevalence of hepatic steatosis, which was more evident in men." (PMID 36160146, 2022). "PGE2 acts with insulin in the pathogenesis and progression of hepatic steatosis." (PMID 36296994, 2022). "This notwithstanding these findings raise the intriguing possibility that a potential mechanism underpinning (at least in part) the effect of cixutumumab on hepatic steatosis may be enhanced hepatic insulin sensitivity." (PMID 35734881, 2022). "We hypothesized that CRMP might increase longevity due to its ability to prevent the formation of ROS, as well as improve insulin sensitivity, hepatic steatosis, and hepatic inflammation." (PMID 35088525, 2022). "The decrease in insulin sensitivity, particularly in the liver, leads to an increase in hepatic gluconeogenesis, glucose production, and lipogenesis, which may exacerbate hepatic steatosis." (PMID 35448486, 2022). "In summary, we reported that HtrA2/Omi expression could greatly reduce liver steatosis, improve glucose tolerance and hepatic insulin resistance in a mouse model of HFD-induced NAFLD." (PMID 35449197, 2022). "SCFAs can reduce the expression of peroxisome proliferator-activated receptor-γ (PPAR-γ), leading to the increased oxidative metabolism of the liver and adipose tissue, reduced body fat accumulation, and hepatic steatosis, as well as increased insulin sensitivity." (PMID 35215411, 2022). "Interestingly, the imbalance of EDA expression in the liver, especially the EDA-A2 subtype, is increased in hepatic steatosis, which can lead to the deterioration of insulin sensitivity and glucose homeostasis in muscle." (PMID 36012178, 2022). "In addition, FGF21 agonists improve hepatic and systemic insulin sensitivity, leading to a reduction in hepatic steatosis." (PMID 36012166, 2022). "Moreover, we recently found that CRMP is sufficient to reduce dyslipidemia, hepatic steatosis, and hepatic insulin resistance in spontaneously obese non‐human primates due to subtle sustained increases in hepatic mitochondrial oxidation." (PMID 35088525, 2022). "Since the elimination of senescent cells by treatment with a combination of the senolytic drugs dasatinib plus quercetin (D + Q) reduces overall hepatic steatosis in ageing, obese and diabetic mice, we tested the efficacy of this treatment in preventing insulin-induced hepatocyte senescence." (PMID 35872305, 2022). "In addition, piperine (50 mg/kg bw) improves insulin signaling in HFD-induced hepatic steatosis by reversing the plasma adiponectin, insulin, and glucose concentration." (PMID 35127957, 2022).
Hepatic steatosis (continued). "In the liver, excessive DNL leads to hepatic steatosis linked with lower hepatic insulin sensitivity but, in AT, DNL produces several insulin-sensitizing lipokines and positively regulates adipocyte membrane fluidity and insulin signaling." (PMID 36232405, 2022). "In this study, disruption of intestinal HIF2α in mice reduced intestinal and circulating ceramide levels during high-fat diet feeding (most notably C16:0 ceramides), accompanied by reductions in body weight gain and hepatic steatosis, and improvements in systemic insulin sensitivity." (PMID 35789435, 2022). "Other studies have shown that high adropin levels improve insulin sensitivity and carbohydrate and lipid metabolism while suppressing hepatic steatosis, suggesting that restoring proper adropin levels can be a valuable therapeutic approach for the treatment of NAFLD." (PMID 36014766, 2022). "Furthermore, promoting macrophage M2 polarization decreases inflammation and increases browning markers in adipose tissue, reduces hepatic steatosis and restores glucose tolerance and insulin sensitivity in HFD-fed mice." (PMID 35112705, 2022). "A study that used Mendelian Randomization analysis to evaluate the relationship between NAFLD and plasma insulin clearance based on genetics, also found no support for a causal link between hepatic steatosis and hepatic insulin clearance." (PMID 35054781, 2022). "An interaction network based on DELs and differential genes (DEGs) suggested that QGD inhibited hepatic steatosis mainly by reducing hepatic insulin resistance and triglyceride biosynthesis via the PPP1R3C/SIK1/CRTC2 and PPP1R3C/SIK1/SREBP1 signal axis, respectively." (PMID 36452137, 2022). "Moreover, reduction of Pacs-2 levels also results in improved insulin sensitivity and improved liver steatosis in ob/ob mice." (PMID 36138342, 2022). "The insulin resistance signaling pathway would result in an imbalance between de novo lipogenesis and β-oxidation, as well as an impairment of the hepatic gluconeogenesis pathway, thereby exacerbating the fat accumulation and the resultant hepatic steatosis." (PMID 35617279, 2022). "Thus, fructose insulin‐independently serves as both a substrate and an inductor of de novo lipogenesis, facilitating liver steatosis." (PMID 35713152, 2022). "Sex hormone dysfunction may contribute to the development of NAFLD, because a reduction in insulin sensitivity increases hepatic gluconeogenesis and lipogenesis, in turn, this may exacerbate hepatic steatosis." (PMID 36482993, 2022). "Reduced liver steatosis in those groups was corroborated by histology, plasma liver enzyme levels, and lipid profile, indicating improved liver function and lipid metabolism in addition to enhanced insulin sensitivity." (PMID 36364811, 2022). "Intestinal flora disorder also affects the metabolic system, including changes in BAs composition, the production of SCFAs from dietary fiber, and the conversion of choline to TMA, thus leads to the disorder of glucose and lipid metabolism, including insulin sensitivity and hepatic steatosis." (PMID 36119048, 2022). "This ‘dose’ of sucrose was effective at increasing adiposity and inducing hepatic steatosis without causing systemic disruptions to insulin responsiveness or glucose tolerance." (PMID 36229459, 2022). "Furthermore, macrophage depletion showed protective effects against hepatic steatosis and IR, while pro‐inflammatory macrophages decreased hepatocyte responsiveness to insulin in vitro." (PMID 35040267, 2022). "Furthermore, inhibition of ceramide biosynthesis using myriocin in rodents improves various features of metabolic diseases such as insulin sensitivity, hepatic steatosis and cardiovascular complications." (PMID 35508667, 2022). "A reduction in ceramides can improve hepatic steatosis and insulin sensitivity." (PMID 35629938, 2022). "In addition to hepatic steatosis, increased muscle insulin sensitivity and decreased adiposity, LPTENKO mice have also a low glycemia." (PMID 35409319, 2022).
Hepatic steatosis (continued). "In addition, activation of iNKT cells by lipid excess contributes to inflammation of the tissue, resistance toward insulin, and hepatic steatosis in obese mice." (PMID 36438786, 2022). "However, restoring HtrA2/Omi ameliorated hepatic steatosis, confirming by improved serum lipid profiles, glucose homeostasis, insulin resistance, histopathological lipid accumulation, and the gene expression related to lipid metabolism." (PMID 35449197, 2022). "We hypothesized that the symbiotic interaction among these products would improve the absorption of nutrients, triggering a decrease in fatty liver diseases through inflammatory pathways and oxidative stress modulation, thus improving insulin sensitivity." (PMID 35326098, 2022). "The TULIP study pointed out that low insulin secretion capacity (defined by the 1st-phase insulin secretion marker “disposition index”) and insulin-resistant fatty liver are independent risk factors for lifestyle non-response." (PMID 36432409, 2022). "PPARδ further reduced the expression of PTEN to enhance insulin sensitivity in hepatic steatosis." (PMID 34140896, 2021). "We report neurotransmitter signaling by which hepatic steatosis may induce systemic insulin dysregulation, while establishing that hepatocyte GABA release is regulated by hepatocyte membrane potential." (PMID 34192533, 2021). "In addition, we show that the effects of PLIN5 in BAT secondarily lead to smaller adipocytes in iWAT, to improved systemic glucose tolerance and insulin sensitivity, and to protection from hepatic steatosis on a high-fat diet (HFD)." (PMID 34083525, 2021). "Because changes in CB1R expression interfere with the insulin transmission pathway, they may also indirectly contribute to liver steatosis." (PMID 33498537, 2021). "Damage to tight junctions will causes increases in inflammation and oxidative stress, and excessive inflammation can jeopardize insulin signaling pathways and fatty acid metabolism, subsequently aggravating insulin resistance and liver steatosis and ultimately exacerbating NAFLD." (PMID 33708180, 2021). "Experimental evidence based on both human hepatocytes and animal models also suggests that GLP-1 RAs are able to improve hepatic steatosis by reducing de novo lipogenesis, enhancing oxidation of fatty acids and improving multiple elements of the insulin signaling pathways." (PMID 33513761, 2021). "GLP-1 receptors have been documented in mice and human hepatocytes, and the activation of such receptors may promote the reduction of hepatic steatosis by improving insulin-signaling pathways, hepatocyte lipotoxicity, and mitochondrial function." (PMID 33652942, 2021). "We and others have demonstrated that modulation of adipocyte lipolysis via genetic ablation or pharmacological inhibition of ATGL improves systemic glucose homeostasis and insulin sensitivity, and protects against hepatic steatosis in the setting of diet- or genetically induced obesity." (PMID 33692445, 2021). "SREBP-1c not only transduces the insulin signal but is also involved in the hepatic steatosis." (PMID 33726778, 2021). "In conclusion, crosstalk between β‐AR and insulin signaling may contribute to HFD‐induced hepatic steatosis through ERK1/2‐ and AKT‐mediated hyperactivation of the mTORC1/S6K1 axis." (PMID 34231324, 2021). "Indeed, the hepatic steatosis-preventing effects of XOS were associated with decreased adipose tissue inflammation, likely improved insulin signaling and certain clusters of co-occurring fecal metabolites and bacterial genera." (PMID 33921370, 2021). "The agonistic activity on FXR was beyond the pharmacological role of UDCA, while obeticholic acid acting as a FXR agonist could significantly improve hepatic steatosis and increase insulin sensitivity in NASH patients." (PMID 34938193, 2021). "Furthermore, non-invasive hepatic steatosis indices correlated positively with fasting blood insulin and C peptide level, TG, TC, LDL-C, but negatively with HDL-C." (PMID 34400897, 2021).
Hepatic steatosis (continued). "The strict connection between fatty liver and impaired insulin sensitivity has been documented, but considering the complexity of links between NAFLD, IR, and T2DM, it is extremely difficult to find out whether NAFLD is the effect or the cause of IR." (PMID 33804296, 2021). "Decreased VLDL secretion or aberrant insulin signaling did not cause hepatic steatosis in Mboat7 LSKO mice." (PMID 32859645, 2021). "Liver-specific SIRT6 knockout increased hepatic insulin sensitivity in female, but not male mice, although was independently reported to cause fatty liver." (PMID 34046015, 2021). "Moreover, another work in this lab showed that sequestration of intestinal endotoxin via cholestyramine, cationic polymeric resins, can profoundly resolve systemic inflammation, restore insulin sensitivity, and attenuate hepatic steatosis and liver fibrosis." (PMID 34764881, 2021). "Moreover, glucose tolerance and insulin sensitivity were all significantly reduced, and hepatic steatosis was prevented." (PMID 34441564, 2021). "Chronically decreased PC expression in liver and adipose tissue was demonstrated to reduce plasma glucose concentrations, the rate of endogenous glucose production, adiposity, plasma lipid concentrations, hepatic steatosis and improved hepatic insulin sensitivity." (PMID 34063343, 2021). "In the same study, ILG supplement (0.5% w/w) in the HFD reduced body weight gain (despite similar food intake), improved glucose tolerance and insulin sensitivity, inhibited hepatic steatosis, and suppressed inflammation in epididymal white adipose tissue (eWAT)." (PMID 33535473, 2021). "This suggests that HFrD may impair hepatic insulin clearance, which can also contribute to hepatic steatosis." (PMID 33972568, 2021). "A study found that a moderate-intensity exercise training program did not cause weight loss in HFD-fed group and did not have significant changes in insulin sensitivity and liver inflammation but decreased liver steatosis caused by HFD." (PMID 34054726, 2021). "Direct genetic modulation of enzymes affecting the ceramide pathways in mice like dihydroceramide desaturase 1 may drive insulin resistance and hepatic steatosis." (PMID 33417276, 2021). "For instance, adipocyte-selective overexpression of PFKFB3/iPFK2, which activates 6-phosphofructo-1-kinase (6PFK1) to enhance glycolysis, decreased HFD-induced liver proinflammatory response and improved insulin signaling; although leading to increased hepatic steatosis." (PMID 36994336, 2021). "With respect to inhibiting the inflammatory response and oxidative stress, genistein was reported to ameliorate fatty liver in insulin-resistant rats by activating the antioxidant profile, decreasing IL6 and TNF-α concentrations and preventing oxidative damage." (PMID 33953784, 2021). "However, the study by Tao showed that adipocyte-specific TLR4 deletion in mice significantly increased the severity of HFD-induced hepatic steatosis while improving systemic insulin sensitivity." (PMID 34943809, 2021). "Our study shows that daily insulin treatment of the diabetic rats prevented hepatic steatosis." (PMID 34270619, 2021). "Besides, the reduction of glycogen synthase accelerates hepatic insulin resistance and liver steatosis, and vice versa." (PMID 33628322, 2021). "Similarly, second generation antisense oligonucleotides that were targeted to hepatic mIndy prevented diet-induced hepatic insulin resistance and hepatic steatosis in rats." (PMID 35822025, 2021). "In this regard, the administration of IAP to mice fed a high-fat diet prevents endotoxemia and the associated metabolic syndrome, while Akp3 (duodenal AP) knock-out mice show faster weight gain, visceral fat accumulation and hepatic steatosis, as well as insulin resistance." (PMID 33374541, 2020).